MMP12 (matrix metallopeptidase 12)
Diseases named in the same sentence as MMP12 in open-access papers (continued):
Sharing a sentence is not in itself a finding about the gene and the disease.
atherosclerosis (54 papers, 2011 to 2026). A disease characterized by the build-up of fatty material and calcium deposition in the arterial wall resulting in partial or complete occlusion of the arterial lumen. "Studies also found the levels of MMP1, MMP3, and MMP12 were positive associated with the degree of atherosclerosis and plaque stability, acting as valuable biomarkers for clinical diagnosis and prognosis of atherosclerosis." (PMID 37006258, 2023). "We investigated the impact of MMP12 deficiency on CMDs in a mouse model that mimics human disease by simultaneously developing adipose tissue inflammation, insulin resistance, and atherosclerosis." (PMID 38017481, 2023). "Coronary arteries from Apoe/MMP-12 double knockout mice displayed significantly reduced atherosclerosis which was associated with a decreased incidence of sudden death over the course of thirty-six weeks of high-fat feeding." (PMID 34848763, 2021). "In our cohort, MMP12 was elevated in patients with previous atherosclerosis, although the association was lost after adjusting for confounding factors." (PMID 34062730, 2021). "Increased activity of MMP-12, predominantly produced by macrophages, is associated with atherosclerosis." (PMID 33781257, 2021). "Previous studies reported association between CRP and atherosclerosis, and MMP12 and atherosclerotic burden." (PMID 34062730, 2021). "We also show that mRNA expression of the nearest gene (MMP12) is higher in arteries with the disease process underlying large artery stroke (atherosclerosis)." (PMID 25078452, 2014). "MMP-12 is expressed in macrophages and epithelial cells and has been implicated in the progression of atherosclerosis, wound repair, and certain cancers." (PMID 21887284, 2011). "Moreover, studies utilizing mice with MMP-12-deficiency or MMP-12 specific inhibition to assess effects on atherosclerosis have reported reduced medial elastin destruction, implicating a role for MMP-12 in atherosclerotic aneurysm formation." (PMID 38891996, 2024). "Studies showed that the overexpression of MMP12 was associated with atherosclerosis." (PMID 37978381, 2023). "Likewise, when PERI-cell-derived constructs were supplemented with 800 μM vitamin C, MYH7 was downregulated, as was the matrixmetalloproteinase-encoding gene MMP12, which is a macrophage metalloelastase commonly implicated in atherosclerosis." (PMID 38069418, 2023). "Finally MMP-12 seemed primarily a marker of atherosclerosis, but was also significantly associated with the combination of COPD and plaque even when adjusting for several risk factors." (PMID 30789935, 2019). "The proteolytic activity of MMP12 could further decrease the integrity of the endothelium and increase the risk of atherosclerosis and plaque rupture." (PMID 31114450, 2019). "Additionally, MMP-12 has been associated with symptomatic atherosclerosis." (PMID 37160529, 2023). "Thus, differential abundance of proteins associated with vasorelaxation and ROS production, downregulation of the ROS pathway, and myography data indicate that MMP12 deficiency improves endothelial dysfunction, which is considered an early stage in the development of atherosclerosis." (PMID 38017481, 2023). "We conclude that besides its beneficial effects on insulin sensitivity, systemic inflammation, and atherosclerosis, the deletion of MMP12 improves brown adipose tissue function in cardiometabolic conditions." (PMID 41308745, 2025). "We have previously demonstrated that the genetic deletion of MMP12 in a cardiometabolic mouse model ameliorates obesity-induced low-grade inflammation, white adipose tissue dysfunction, and atherosclerosis." (PMID 41308745, 2025). "Human abdominal aortic aneurysms (AAAs) are characterized by increased activity of matrix metalloproteinases (MMP), including MMP-12, alongside macrophage accumulation and elastin degradation, in conjunction with superimposed atherosclerosis." (PMID 38891996, 2024).
atherosclerosis (continued). "Accordingly, it is plausible that MMP-12 can exert disparate effects during different phases of aneurysm formation and progression, especially in the absence/presence of atherosclerosis-related inflammation." (PMID 38891996, 2024). "This study found by network analysis that MMP12 was highly expressed in both atherosclerosis and NSCLC." (PMID 37978381, 2023). "In patients with type 2 diabetes (TDM2), which is a risk factor of atherosclerosis and elevates the risk of stroke in patients with AF, MMP-7 and MMP-12 plasma levels were increased in comparison with patients without glucose metabolism disturbances." (PMID 36835040, 2023). "In atherosclerosis, however, that same MMP-12 inhibitor was beneficial, confirming disease-specific effects of MMPs." (PMID 37160529, 2023). "MMP12-selective inhibitors have already been successfully tested in mouse models of allergic asthma, progression of osteoarthritis, and atherosclerosis." (PMID 38017481, 2023). "MMP9 and MMP12 promoted vascular smooth muscle cell proliferation via beta-catenin pathway and contributed to atherosclerosis." (PMID 37006258, 2023). "In atherosclerosis, a subset of Lgals3- macrophages exhibiting highly expressed Mmp12 accumulated in the advanced plaques with pro-inflammatory characteristics." (PMID 37359523, 2023). "We identified 15 identical pathogenic genes, and four of which (MMP9, MMP12, CD36, and FABP4) were considered as the key target genes of atorvastatin in anti-atherosclerosis and NSCLC." (PMID 37978381, 2023). "Published data from humans, rabbits, or other mouse models have already described detrimental effects of MMP12 on atherosclerosis development." (PMID 38017481, 2023). "We conclude that the genetic deletion of MMP12 ameliorates obesity-induced low-grade inflammation, white adipose tissue dysfunction, biomechanical properties of the aorta, and the development of atherosclerosis." (PMID 38017481, 2023). "In atherosclerosis, MMPs play a dual role: in fact, some MMPs (i.e., MMP-12) are beneficial, and others (i.e., MMP-9) appear to be harmful." (PMID 36865918, 2023). "Using this unique model, we have demonstrated that increased MMP-12 expression enhances the development of atherosclerosis and inflammatory arthritis." (PMID 36704203, 2022). "Our findings strengthen the call for therapeutic clinical trials targeting MMP-12 for the prevention of atherosclerosis." (PMID 34848763, 2021). "The purpose of this study was to evaluate prospectively the circulating levels of MMP12 and SDF1 in a cohort of patients with clinical and subclinical atherosclerosis and its role as biomarkers of high risk of CVD and worse outcome." (PMID 34062730, 2021). "Collectively, these findings delineate galectin-3 as a negative regulator of inflammation and macrophage invasion that opposes adverse atherosclerosis progression and confirms MMP12 as a potential target for medical intervention of atherosclerosis." (PMID 32295421, 2020). "As such, MMP-12 is upregulated in several inflammatory diseases, including abdominal aortic aneurysm and atherosclerosis." (PMID 31561608, 2019). "This raises the exciting possibility of a role for MMP-12 imaging in detecting the sites of early atherosclerosis prior to florid disease." (PMID 27917892, 2016). "mRNA expression of the two proximal genes, MMP3 and MMP12 was analysed from 29 carotid, 15 abdominal aorta, 24 femoral plaques, and 28 atherosclerosis free left internal thoracic artery controls." (PMID 25078452, 2014). "The nearby gene, MMP12, was significantly overexpressed in carotid plaques compared to atherosclerosis-free control arteries (p = 1.2×10−15; fold change = 335.6)." (PMID 25078452, 2014). "Selective inhibition of MMP‐12 was reported to retard atherosclerosis progression with a more fibrous plaque in mice." (PMID 24744893, 2014).
atherosclerosis (continued). "From our present data, lowered prevalence of MMP-12–positive macrophages appears to be another factor possibly related to the protective effect of female sex on atherosclerosis." (PMID 23316311, 2012). "A recent study found that MMP-12 production by macrophages plays a role in the transition from fatty acids to fibrous plaques during the progression of atherosclerosis." (PMID 21887284, 2011). "Five of them (ANGPTL4, APOB, BRAP, LPA, and ZPR1), were associated with increased levels of arteriosclerosis/atherosclerosis and risk of CVD, whereas four (DUSP13, FN1, IL6R, and MMP12) were associated with reduced levels of arteriosclerosis/atherosclerosis and risk of CVD." (PMID 42133815, 2026). "Here we found an increased expression of MMP-1 and MMP-12 associated with stimulated cell migration of macrophages induced by PFOS and PFOA, which supports the role of macrophages in PFAS-mediated development of foam cells and atherosclerosis." (PMID 40728694, 2025). "MMP-12, a metalloelastase initially identified in the alveolar macrophages of smokers, has been shown to negatively impact plaque stability in a mouse model of brachiocephalic artery atherosclerosis." (PMID 40305314, 2025). "The use of an MMP-12 inhibitor resulted in a significant reduction in plaque formation, necrosis, calcification, and macrophage apoptosis, leading to thinner fibrous plaques and the slower progression of atherosclerosis." (PMID 40305314, 2025). "The role of MMP-12 (also termed macrophage metalloelastase) has been explored in a multitude of cardiovascular diseases, with a pro-inflammatory and deleterious function demonstrated in atherosclerosis." (PMID 38891996, 2024). "Conversely, previous evidence suggests in the absence of atherosclerosis and associated inflammation, MMP-12 protects the integrity of the aortae and prevents acute dilation and subsequent aortic dissection." (PMID 38891996, 2024). "MMP-12 is preferentially expressed by macrophages and facilitates monocyte/macrophage accumulation at sites of injury and during multiple inflammatory diseases such as atherosclerosis." (PMID 38891996, 2024). "Additionally, several studies using different animal models of adipose tissue inflammation and insulin resistance or atherosclerosis have indicated a pathological role of MMP12 in T2D and CVD." (PMID 38017481, 2023). "The atherosclerosis burden was decreased in Mmp-7 and Mmp-12 knockout animals but enhanced in Timp-1-devoid animals, as well as the degree of coronary arteries stenosis, whereas post-infarction cardiac fibrosis was increased in Mmp-7 as and markedly reduced in Timp-1-deficient mice." (PMID 36835040, 2023). "It would be interesting to examine whether the administration of a MMP-12 specific inhibitor prevents the formation of atherosclerosis in vivo." (PMID 36704203, 2022). "Recent studies have revealed that increased expression of matrix metalloproteinase-12 (MMP-12) derived from macrophages may be particularly important in the pathogenesis of both atherosclerosis and AAA." (PMID 36704203, 2022). "In this respect, we were specifically interested in the role of MMP-12, an important elastase secreted from macrophages, which has been shown to play diverse roles in inflammatory processes such as arthritis, atherosclerosis, and AAA." (PMID 36704203, 2022). "In addition, Mmp8 and Mmp12 levels were reduced in Trib3KO macrophages, whose depletion in human diseased arteries and animal models of atherosclerosis results in reduced plaque size and increased collagen content, therefore improving plaque stability." (PMID 36158793, 2022). "Furthermore, MMP12 has been proposed as a potential biomarker of CVD in patients with type 2 diabetes, while its deficiency reduced atherosclerosis development and macrophage infiltration in murine models." (PMID 34062730, 2021). "SDF1/CXCR4 axis and MMP12 involvement in atherosclerosis development suggests that they could be possible atherosclerotic targets." (PMID 34062730, 2021).
atherosclerosis (continued). "Previous study has verified that elevated SASP mRNA expression (including Il-1α, Tnf-α, Ccl2, Mmp12, and Mmp13) significantly increases in senescent foamy macrophages during atherosclerosis, which has the similar characteristics of SASP in senescent macrophages during lung fibrosis." (PMID 34023858, 2021). "In an ApoE-/- mice model of atherosclerosis, this compound induced a change in atherosclerotic plaques composition, thus limiting their evolution towards an instable phenotype, strongly suggesting MMP12 as a relevant target in this model." (PMID 31561608, 2019). "Furthermore, increased expression of MMP12 is associated with elevated expression of MMP3 and participates in the progression of atherosclerosis in transgenic rabbits." (PMID 30187887, 2018). "Matrix metalloproteinase-12 (MMP-12) promotes atherosclerosis in animal models." (PMID 23316311, 2012). "An increased circulating concentration of MMP7 and MMP12 may indicate active extracellular matrix remodeling that is involved in degrading the elastic layers and/or cell membranes basement with promotion of initiation and progression of atherosclerosis." (PMID 40272732, 2025). "Thus, our data indicate that genetic deletion of MMP12 leads to multiple changes in the vascular wall, which may protect the mice from cardiovascular disease, including atherosclerosis." (PMID 38017481, 2023). "While the contrasting roles for MMP-12 in atherosclerosis and post-MI remodelling may be ascribed to different cell sources and substrates, and chronic versus acute inflammatory responses, respectively, hypercholesterolaemia and underlying atherosclerosis may also explain the divergent observations." (PMID 34848763, 2021). "Our findings lend further support to MMP12 as a pertinent therapeutic target for the prevention of clinical atherosclerosis and suggest that promoting galectin-3 expression may also represent an effective strategy to counter the actions of proinflammatory macrophages during plaque progression." (PMID 32295421, 2020). "In conclusion, MMP9, MMP12, FABP4, and CD36 genes are closely related to the occurrence and development of atherosclerosis and NSCLC." (PMID 37978381, 2023). "Atorvastatin inhibits atherosclerosis and NSCLC by down-regulating the expression of MMP9, MMP12, FABP4, and CD36." (PMID 37978381, 2023). "Other studies have shown that the involvement of MMPs in atherosclerosis leads to a reduction in atherosclerotic lesions when using double knockout animals for ApoE-⁄- and MMP-2-⁄-, MMP-8-⁄-, and MMP-9-⁄- and MMP-12-⁄-." (PMID 35269673, 2022). "Patients with clinical atherosclerosis showed increased levels of SDF1 (2.7 ± 0.9 ng/mL vs. 2.3 ± 0.5 ng/mL, p < 0.001), MMP12 (501 pg/mL vs. 358.5 [241.5–553.5] pg/mL, p = 0.002) and CRP (0.24 [0.13–1] mg/dL vs. 0.12 [0.07–0.31] mg/dL, p < 0.001)." (PMID 34062730, 2021). "RESULTS: SDF1, MMP12 and CRP were elevated in patients with clinical atherosclerosis, but after controlling by confounding factors, only SDF1 and CRP remained increased." (PMID 34062730, 2021). "Together, these findings strongly indicate that galectin-3 acts as a negative regulator of inflammation by modulating TGFβ signaling and reducing the expression of the proinflammatory molecules MMP12, CCL2, and PTGS2 in a mouse model of atherosclerosis." (PMID 32295421, 2020). "Mediators involved in atherosclerosis (CX3CL1/fractalkine, CCL8, M-CSF, CXCL5, CCL4, HGF), tissue remodeling (MMP-12, MMP-1, MMP-10) and angiogenesis (VEGF-A) were also increased in AD." (PMID 28821884, 2017). "Here, we demonstrated that genetic deletion of MMP12 improved the cardiometabolic phenotype, altered immune cell composition, ameliorated low-grade systemic inflammation and WAT function, improved insulin resistance, and reduced atherosclerosis development." (PMID 38017481, 2023). "We hypothesized that atorvastatin could inhibit the expression of MMP9, MMP12, FABP4, and CD36 in patients with atherosclerosis and NSCLC." (PMID 37978381, 2023).
atherosclerosis (continued). "After overlapping the 431 putative targets of atorvastatin with 15 common pathogenic genes between atherosclerosis and NSCLC, then find 4 genes (MMP9, MMP12, CD36, and FABP4) were identified as potential therapeutic targets of atorvastatin for atherosclerosis and NSCLC." (PMID 37978381, 2023). "MMP9, MMP12, FABP4, and CD36 might be the potential therapeutic targets in treating atherosclerosis and NSCLC." (PMID 37978381, 2023). "Out of 249 genes in significant modules that were not enriched in pathways or networks, four genes, LMNA and MMP12 at baseline, NPY and RXRA in females and males at 2y have previously been shown to be associated with atherosclerosis." (PMID 35925965, 2022). "The absence of adverse consequences on cardiac fibrosis with MMP-12 deficiency, supports targeting of MMP-12 for the treatment of unstable atherosclerosis." (PMID 34848763, 2021). "The level of MMP-12, which can hydrolyze elastin and intercellular matrix proteins, as well as activating MMP-3 and MMP-2, was statistically significantly higher in the group of men with atherosclerosis—2.1 times compared to the control group." (PMID 34205079, 2021). "However, both T3 treatment groups in established atherosclerosis significantly reduced MMP-9 and MMP-12 tissue expression compared to T3-negative rabbits group suggesting its potential role in attenuating progression of plaque instability." (PMID 27799085, 2016). "Even though there is evidence of MMP-12 activity in cardiovascular pathologies such as aortic aneurysms and atherosclerosis, to our knowledge there is no pre-existing evidence directly implicating MMP-12 activity in cardiac remodeling." (PMID 22768802, 2012). "Taken together, these lines of evidence suggest a consistent deleterious effect of MMP-12 on aneurysm formation in the presence of atherosclerosis and accompanying macrophage-enriched inflammation, while in the absence of atherosclerosis and marked inflammation the role of MMP-12 is less clear." (PMID 38891996, 2024). "In addition, genetic deletion of MMP12 ameliorates cardiometabolic diseases by reducing circulating lipid levels, obesity-induced low-grade inflammation, WAT dysfunction, insulin sensitivity, and atherosclerosis in a room temperature-housed cardiometabolic mouse model." (PMID 41308745, 2025). "Therefore, atorvastatin might inhibit atherosclerosis and NSCLC by inhibiting MMP12." (PMID 37978381, 2023).